RN7SKP254 (RN7SK pseudogene 254)
Gene: Miscellaneous RNA gene on chromosome 15 (96,486,582 to 96,486,891, forward strand). Ensembl gene ENSG00000222617.
Homologues: Orthologues: chimpanzee 7SK (98% identical), guinea pig 7SK (58% identical), mouse Gm54406 (53% identical). Paralogues in human: 7SK (70% identical), RN7SKP133 (70% identical), RN7SKP255 (70% identical), RN7SKP204 (69% identical), RN7SKP243 (69% identical), RN7SKP173 (69% identical), RN7SKP37 (69% identical), RN7SKP250 (68% identical), RN7SKP30 (68% identical), RN7SKP71 (68% identical), RN7SKP176 (68% identical), RN7SKP20 (68% identical), and 284 more.